AR (androgen receptor)
Diseases named in the same sentence as AR in open-access papers (continued):
Sharing a sentence is not in itself a finding about the gene and the disease.
prostate carcinoma (continued). "AR co-regulators implicated in prostate cancer progression also include transcription factors, such as members of the ETS domain family of transcription factors that recognize ETS binding motifs in the genome." (PMID 33513133, 2021). "The loss of AR expression during prostate cancer progression occurs as part of a larger cellular rewiring process that is paralleled by dramatic changes in cellular differentiation." (PMID 33420371, 2021). "An emerging clinical problem arising from the increased use of potent AR-targeted therapies is prostate cancer lineage plasticity associated with NEPC and reduced/lost dependence on AR36." (PMID 34737261, 2021). "Targeting prostate-specific antigens whose expression is closely linked to the activity in the androgen receptor pathway, and thus the pathogenesis of prostate cancer, is a possible way to increase specificity and reduce off-target effects." (PMID 34959652, 2021). "Low levels or complete loss of AR also coincided with reduced 4EBP1 expression in AR-low/null human AR program-independent prostate cancer cell line and metastatic castration-resistant PC (CRPC) LuCaP patient-derived xenografts (PDXs)." (PMID 34209750, 2021). "While we were undertaking this work, a paper reported the presence of a prostate cancer risk single-nucleotide polymorphism, rs684232, that suppresses AR-dependent expression of GEMIN4." (PMID 34725334, 2021). "Androgen signaling and subsequent AR activation is a hallmark of prostate cancer progression and surprisingly has long been known to downregulate PSMA." (PMID 34067046, 2021). "Most studies focus on hormone-resistance mechanisms related to androgen receptor mutations or to the acquired property of prostate cancer cells to over-activate signaling pathways." (PMID 33500395, 2021). "Although responsive to ADT at the beginning, most prostate cancers become ADT-resistant over time due to the formation of constitutively active AR variants or the activation of AR by other factors." (PMID 33535458, 2021). "This study offers a potential new marker, the androgen receptor/filamin A complex, and a new therapeutic approach targeting intracellular pathways activated by the androgen/androgen receptor axis in prostate cancer-associated fibroblasts." (PMID 33500395, 2021). "Rationale: Aberrant androgen receptor (AR) signaling via full-length AR (AR-FL) and constitutively active AR variant 7 (AR-V7) plays a key role in the development of castration-resistant prostate cancer (CRPC) and resistance to hormone therapies." (PMID 33391515, 2021). "On the other hand, in prostate cancer the acetylation on H2A.Z (K4, K7, and K11) allows greater chromatin accessibility, contributing to the activation of androgen receptor-associated enhancers and gene expression." (PMID 35317119, 2021). "Some mutations in the androgen receptor also impact the androgen-β-catenin axis and hence, lead to the progression of prostate cancer." (PMID 35201496, 2021). "Our findings suggest therapeutic potential for co-inhibition of the MAPK and AR pathways in BRAF-mutated prostate cancers." (PMID 34211036, 2021). "HECTD4 is an E3 ubiquitin ligase that is associated with androgen receptor promotion in prostate cancer cell lines." (PMID 34828409, 2021). "Over 20 AR variants (AR-Vs) have been identified to co-express with wild-type AR in human prostate cancer cell lines, xenografts or clinical specimens." (PMID 33993099, 2021). "Multiple transcription factors involved in cellular plasticity and AR independence have been linked to prostate cancer progression to AR-negative disease." (PMID 33420371, 2021). "We selected to screen the mRNA expression levels of AR variants V1, V3, V7 and V12, because these variants have been described as the most abundant variant transcripts in prostate cancer." (PMID 34490120, 2021).
prostate carcinoma (continued). "B cells can secrete IL-8, a cytokine that is implicated in the activation of the AR and cancer progression through the androgen independent pathway in prostate cancer." (PMID 33919565, 2021). "The androgen receptor (AR) is expressed in many cell types and, while most studies have focused on prostate cancer, AR signaling has been implicated in tumorigenesis in other organs, specifically breast, bladder, kidney, lung, and liver." (PMID 33112375, 2021). "Loss of the tumor suppressor PTEN frequently occurs from deletion or mutation and is associated with increased prostate cancer progression, AR-independent growth and poor patient prognosis." (PMID 34439133, 2021). "Xenoestrogens such as BPA have been reported to contribute to obvious gene expression in prostate cancer cells with somatic AR mutations." (PMID 34084133, 2021). "The AR is a specific oncogene especially implicated in prostate cancer as AR-directed transcription (androgen dependent/independent) allows growth of the tumor in all stages of prostate cancer." (PMID 34884434, 2021). "KDM4A overexpression was found to stimulate the AR, inducing the expression of prostate specific antigen, implicated in the progression of prostate cancer." (PMID 34220955, 2021). "Previous work has revealed that the dual PI3K/mTOR inhibitor dactolisib (BEZ235) promotes AR signaling in a HER2/3 dependent manner in PTEN-deficient prostate cancer models, while AR-targeted therapy augments AKT signaling." (PMID 33105713, 2020). "On the contrary, genes whose loss/down-regulation was implicated in prostate cancer cell invasion, metastasis formation and worse prognosis (AR, IGF1, IGF2, TGFB3, SEMA3E) were down-regulated in NE-like versus AdenoPCa tumors." (PMID 32041153, 2020). "Nuclear localization of these additional AR-Vs results in the enhanced activation of canonical AR targets and splice variant specific targets which consequently increases the severity of prostate cancer." (PMID 35582225, 2020). "Adaptation mechanisms include prostate cancer cell gene mutations, androgen receptor mutations, and androgen receptor gene overexpression." (PMID 33336042, 2020). "Contrary to an earlier study, which had found that dysregulation of the expression of AR was the only event associated with all stages of prostate cancer, we found an additional nine splicing events." (PMID 32820253, 2020). "For instance, the presence of the alternatively spliced androgen receptor variant 7 (AR-V7) in castration-resistant prostate cancer patients has been linked to a decrease in the effectiveness of hormone-directed therapy." (PMID 33261131, 2020). "For instance, JMJD1A promotes alternative splicing of AR variant 7 (AR-V7) in prostate cancer cells." (PMID 32461996, 2020). "In AR knockout LNCaP cells (human prostate cancer cells), expression of TFAM and several nuclear DNA-encoded or mtDNA-encoded subunits of respiratory chain complexes were increased." (PMID 32932692, 2020). "PRMT5 methylation of the TMPRSS2:ERG fusion protein is commonly seen in prostate cancer (PC) and implicated in prostate tumor formation by inhibiting AR -dependent transcription." (PMID 32743345, 2020). "AR splice variants were already detected in BC patients and AR-V7 was reported to cause resistance to anti-AR therapies in prostate cancer." (PMID 31254045, 2020). "Cancer systems biology analysis also highlights the role of histone demethylases on the generation of constitutively active forms of AR variants associated with progression of prostate cancer." (PMID 33243086, 2020). "The suppressed AR translocation caused a reduction in AR transactivation and thus retardation of prostate cancer cell growth." (PMID 33321809, 2020). "In corroboration, resistance to the AKT inhibitor capivasertib (AZD5363) in LNCaP prostate cancer xenografts is also associated with elevated AR signaling, and combining AZD5363 treatment with the antiandrogen bicalutamide prolonged disease stabilization." (PMID 32630372, 2020).
prostate carcinoma (continued). "The expression of the androgen receptor (AR) and its splice variant AR-V7 is crucial for prostate cancer (PCa) biology." (PMID 32947898, 2020). "Expression of NCOA3 has been associated with increased AR activation in prostate cancer and urothelial carcinoma of the bladder in humans." (PMID 32854182, 2020). "High androgen receptor splice variant 7 (ARV7) mRNA or protein expression level in CTCs from patients with advanced prostate cancer is associated with resistance to therapy with enzalutamide and abiraterone to target androgen receptors." (PMID 32260071, 2020). "In humans, several conditions are associated with AR, including androgen insensitivity syndrome, benign prostatic hyperplasia, and prostate cancer." (PMID 33277473, 2020). "For example, copy number gain of androgen receptor is critical for progression of prostate cancer and is associated with castration resistance." (PMID 32593194, 2020). "It is worthwhile to further investigate its ability to degrade AR variants such as ARv7 and Arv567 which highly associated to castration resistance and metastasis of prostate cancer." (PMID 32842649, 2020). "Androgen receptor (AR) action is a hallmark of prostate cancer (PCa) with androgen deprivation being standard therapy." (PMID 32198885, 2020). "Androgen receptor splice variants (AR-Vs) are also involved in the progression of prostate cancer, as well as the development of resistance to antiandrogens." (PMID 35582225, 2020). "The same Alanine to Valine change (p.A749V) was described as a somatic variant in prostate cancer and estimated to have an adverse effect on the androgen receptor function." (PMID 31936796, 2020). "The ERG interactome, including ERG-associated long-range chromatin, is a collaborative component of higher-order AR-associated chromatin structure and is involved in co-regulating subtypes of AR target genes in prostate cancer." (PMID 32634370, 2020). "Variants of the AR are constitutively expressed in prostate cancer cells and control the activity of cell proliferation, migration, apoptosis and invasion." (PMID 32765953, 2020). "A recent study by Lim and associates has demonstrated that, in prostate cancer cells, Dp44mT and DpC can induce proteasomal degradation of the androgen receptor (AR) via the up-regulation of c-Jun." (PMID 32948029, 2020). "Approximately 30% of advanced-stage prostate cancer patients’ exhibit cellular plasticity and acquisition of altered phenotypes often associated with the loss of AR signaling and/or alteration in AR splice variants." (PMID 33339129, 2020). "Serial analysis of circulating tumor cells (CTCs) such as androgen receptor splice variant 7 is useful in selecting treatments for castration-resistant prostate cancer (CRPC)." (PMID 32373521, 2020). "AR splice variants (AR-Vs) represent a crucial mechanism responsible for castration-resistant prostate cancer progression." (PMID 33333999, 2020). "AR expression has been shown to highly correlate with prostate cancer progression, with AR mutations causing hormone-refractory disease." (PMID 32365531, 2020). "Prostate cancers with a loss of AR function bypass androgen receptor signaling and activate different survival pathways to promote metastasis." (PMID 33182828, 2020). "In prostate cancer patients, high AR expression with low PTEN expression is associated with poor clinical outcomes." (PMID 33062889, 2020). "Despite the approval of new generation AR antagonists, resistance to castration remains one of the major causes of prostate cancer treatment failures, emphasizing the need to identify more potent inhibitors of the androgen axis signaling." (PMID 32560058, 2020).
prostate carcinoma (continued). "The T877S and H874Y mutations in ARs are induced by treatment with androgen receptor (AR) antagonists such as hydroxyflutamide, and a single mutation in the AR transactivates the AR-signaling pathway in the prostate cancer." (PMID 32357493, 2020). "6BIO decreased the drug resistance of the AR splice variant AR-V7 which is important in prostate cancer drug resistance and cancer progression." (PMID 32365809, 2020). "Similar to BPH, the progression of prostate cancer is initially associated with an androgen receptor (AR) signaling pathway." (PMID 32093357, 2020). "There are lots of studies about androgen receptor variants, but relatively less is known about the associations of sex hormones with the growth, proliferation, or progression of prostate cancer." (PMID 32365474, 2020). "Depletion of SPOP in AR-positive, prostate cancer C4-2 cells caused an accumulation γH2AX in the nuclei." (PMID 33023230, 2020). "A total of 32 genes associated with DNA repair are bound by androgen-stimulated AR as demonstrated in the LNCaP prostate cancer cell line model." (PMID 33158305, 2020). "This pattern is disrupted in the setting of CHD1 loss, where aberrant AR cistromes are observed that more closely resemble those seen in prostate cancers." (PMID 32220301, 2020). "PCAT1 interacts with the androgen receptor and lysine-specific demethylase to promote prostate cell growth providing a mechanism by which genetic variants increase risk of prostate cancer." (PMID 31910864, 2020). "This factor suppresses ovarian cancer cell growth and proliferation in vitro, reduces expression of pathogenic APA-induced androgen receptor variant, and up-regulates expression of the full-length androgen receptor in prostate cancer cells." (PMID 32560344, 2020). "AR variants (ARVs) are present both in prostate cancer and breast cancer, and these variants commonly are truncated or have mutations in the AR LBD57." (PMID 33062889, 2020). "Overactivation of androgen receptor (AR)-mediated signal has been extensively implicated in prostate cancer (CaP) development, progression, and recurrence, which makes it an attractive therapeutic target." (PMID 33195208, 2020). "Prostate cancer progression to metastatic disease is associated with increased AR expression and activity." (PMID 32123273, 2020). "The length of the canine AR polyQ tract has previously been associated with aggression in male Japanese Akita Inus and prostate cancer in a variety of breeds." (PMID 32854182, 2020). "The acquisition of resistance to AR-targeted therapy, mainly through neuroendocrine transdifferentiation is a major clinical problem for prostate cancer since it is associated with poor prognosis." (PMID 32256978, 2020). "In this sense,a case-control study was performed that evaluated the possible relationship betweenpolymorphic variants of the genes PTEN, PI3K, AKT1, P504S (AMACR),and AR and prostate cancer susceptibility." (PMID 32484847, 2020). "While, as expected, the AR pathway was universally measured as active in primary prostate cancer, AR pathway activity remained high in some castrate-resistant metastatic prostate cancers, possibly reflecting emergence of AR activating mutations." (PMID 33613616, 2020). "In prostate cancer, it has been shown that AR polysomy is associated with castration-therapy resistance." (PMID 32626651, 2020). "It has been reported that TET2 binds the androgen receptor and its loss is associated with prostate cancer." (PMID 32226005, 2020). "The variation in AR gene polyQ repeats has been associated with prostate cancer, breast cancer, ovarian hyperandrogenism, and Kennedy’s disease." (PMID 32854182, 2020). "Despite the clinical benefits of ADT for the treatment of PCa, emerging evidence has suggested that ADT propels the cancer cells toward therapy-induced resistance and emergence of aggressive AR-independent variants of prostate cancer." (PMID 32754615, 2020).
prostate carcinoma (continued). "Since AR is implicated in all stages of prostate cancer, AR antagonists have been developed for AR-targeted therapy." (PMID 32579541, 2020). "This cohort included patients in which NGS testing revealed positivity for targets such as HER2/neu (ERBB2) in breast cancer specimens, androgen receptor (AR) in prostate cancer, BRAF in melanoma and EGFR mutation in NSCLC." (PMID 32760731, 2020). "AR (androgen receptor) is a transcription factor associated with the development of prostate cancer." (PMID 32251318, 2020). "Metabolic reprogramming is associated with re/activation and antagonism of androgen receptor (AR) signaling that drives prostate cancer (PCa) progression to castration resistance, respectively." (PMID 33163409, 2020). "In prostate cancer, circ_0001427 was found to inhibit enzalutamide resistance by regulating the miR-181c-5p/androgen receptor splicing variant 7 (ARv7) signaling pathway." (PMID 32226514, 2020). "TGFB1I1 (Transforming growth factor beta 1 induced transcript 1) is a coactivator of the androgen receptor, it is known to be associated with prostate cancer, and it can induce EMT, at least in astrocytomes." (PMID 32252623, 2020). "In prostate cancer, androgen receptor spliced variants (AR‐Vs) have been implicated in the carcinogenesis of metastatic prostate cancer, which contribute to resistance to both anti‐androgen therapy and radiotherapy." (PMID 32808488, 2020). "Androgens initially regulate androgen receptor and androgen receptor activity and then, androgen receptor mutation/amplification finally leads to castration-resistant prostate cancer (CRPC) development." (PMID 32365474, 2020). "Nine clinical trials evaluated androgen receptor (AR) splice variants (AR-Vs) in CTCs as marker responsible for castration-resistant prostate cancer progression." (PMID 33333999, 2020). "Evidence suggests that AR variants contribute to the progression of prostate cancer by inducing the transition from epithelial to mesenchymal stem cells, allowing for stem cell migration and expansion." (PMID 32629823, 2020). "Similar to KLK3, also Kallikrein related peptidase 2 (KLK2) functions in hydrolyzing seminogelins and is regulated by androgen receptor, upregulated in prostate tumor cells, and recognized as potential prognostic maker for prostate cancer risk." (PMID 33114768, 2020). "Approximately 20% of advanced prostate cancer patients experience cell plasticity and the acquisition of new phenotypes often associated with loss of androgen receptor signaling." (PMID 32531951, 2020). "Androgens affect gene expression in various kinds of tissues and cells by binding with AR, which has been linked to prostate cancer." (PMID 32790676, 2020). "SPOP mutants associated with prostate cancer fail to interact with and ubiquitinate their substrates, leading to the accumulation of oncogenic substrate proteins such as androgen receptor (AR), BRD2, and BRD4." (PMID 33023230, 2020). "Activation of androgen receptor (AR) splice variants, especially AR-V7, are associated with unfavorable clinical outcome of prostate cancer." (PMID 32489474, 2020). "Gain-of-function mutations in human androgen receptor (AR) are among the major causes of drug resistance in prostate cancer (PCa)." (PMID 32823970, 2020). "Amplifications of the AR and its enhancer are associated with higher levels of AR expression, and over-expressing the AR in prostate cancer cell lines causes enzalutamide-resistance." (PMID 33134178, 2020). "Specific AR germline polymorphisms have been associated with an increased risk of developing prostate cancer, up to six-fold higher compared to the general population (i.e., R725L)." (PMID 33321757, 2020). "Conversely, PI3K-AKT-mTOR pathway inhibition is associated with augmented AR signaling that can contribute to drug resistance and promote prostate cancer progression." (PMID 32630372, 2020).